IL18R1 (interleukin 18 receptor 1)
Diseases named in the same sentence as IL18R1 in open-access papers (continued):
Sharing a sentence is not in itself a finding about the gene and the disease.
pertussis (1 paper, 2024). A contagious bacterial respiratory infection caused by Bordetella pertussis. "Three inflammatory cytokines were found to have a causal relationship with pertussis: IL-4 (OR = 0.3688, 95% CI = 0.16571–0.8208, P = .0145418), IL-18R1 (OR = 1.2757, 95% CI = 1.0499–1.5501, P = .0143), and FGF-21 (OR = 2.0747, 95% CI = 1.0669–4.0341, P = .03147)." (PMID 39612418, 2024). "Additionally, 3 inflammatory cytokines – IL-4, IL-18R1, and FGF-21 – show a causal relationship with pertussis." (PMID 39612418, 2024). "This study also identified 3 inflammatory cytokines (IL-4, IL-18R1, and FGF-21) with causal relationships with pertussis, suggesting that these cytokines may play direct roles in the development of the disease." (PMID 39612418, 2024). "Although IL-4, IL-18R1, and FGF-21 were found to have direct causal relationships with pertussis, the 2-step MR analysis showed that inflammatory cytokines do not mediate the effect of immune cells on pertussis." (PMID 39612418, 2024).
Psychotic episodes (1 paper, 2022). Periods of time during which an individual experiences significant disturbances in their thoughts, perceptions, emotions, and behavior, resulting in a loss of touch with reality. "Further support linking IL-18 signaling to SCZ was the finding that PC5course with positive loadings of IL-18R1, IL-18RAP and APRIL was negatively associated with severity of illness course as measured by rate of psychotic episodes, in these patients." (PMID 35856063, 2022).
infection (40 papers, 2008 to 2025). The state of being infected such as from the introduction of a foreign agent such as serum, vaccine, antigenic substance or organism. "In summary, Il18r1−/− mice presented an intermediary level of susceptibility to infection with T. cruzi, in terms of survival and parasite load in the myocardium, when compared to Myd88−/− and WT (B6) mice." (PMID 28895840, 2017). "On the other hand, Myd88−/− mice are the most susceptible to infection, as all mice of this strain were dead by day 15 pi, while the totality of Il18r1−/− mice were dead only by day 23 pi, a time point at which only 32.5% of WT mice have succumbed." (PMID 28895840, 2017). "Accordingly, Il18r1−/− mice display lower levels of Th1 cells and are highly susceptible to infection, but can be rescued from mortality by the adoptive transfer of WT CD4+ T cells." (PMID 28895840, 2017). "Nevertheless, we clearly demonstrated here that Il18r1−/− mice display low levels of IFN-γ+CD4+ T cells in response to infection with T. cruzi and are highly susceptible to infection." (PMID 28895840, 2017). "Furthermore, we demonstrated the high susceptibility of Il18r1−/− mice to infection with T. cruzi, which could be rescued by the adoptive transfer of WT CD4+ T cells." (PMID 28895840, 2017). "These analyses clearly demonstrated unaltered IL18R1 expression following sham infection and mild infection across any of these mild respiratory virus infections." (PMID 41285788, 2025). "Compared to patients who recovered, patients who later succumbed to A(H7N9) infection had significantly elevated expression of IL18R1." (PMID 41285788, 2025). "To further investigate the role of IL-18 in NK cell metabolism in vivo during infection and inflammation, we generated a mouse model that lacks Il18r1 specifically in NK cells." (PMID 34093543, 2021). "For this, CD4+ T cells were sorted from infected WT mice to high purity levels and were then transferred to both Il18r1−/− and Myd88−/− mice, 20 hr before infection." (PMID 28895840, 2017). "The adoptive transfer of purified WT CD4+ T cells protects Il18r1−/− and Myd88−/− mice against infection with T. cruzi." (PMID 28895840, 2017). "Although Il18−/− mice were shown to be resistant to T. cruzi, discrepancy between the outcomes in Il18r1−/− versus Il18−/− mice was also previously documented for infection with M. tuberculosis and in autoimmunity." (PMID 28895840, 2017). "Importantly, high IL18R1 levels in patients with fatal A(H7N9) infection were detected early after hospital admission and persisted until the patients died." (PMID 41285788, 2025). "Once again, we did not detect any noticeable difference in the expression of these receptors between wild-type and Il18r1-/- mice post LPS infection, indicating that NK cells can upregulate the expression of nutrient transporters in the absence of IL-18 signaling during in vivo inflammation." (PMID 34093543, 2021). "Early infection analysis showed eight markers that were elevated (padj<0.05) in the early infection group compared to the unexposed group, namely TGF-α, HGF, FGF-19, TNFSF14, TRAIL, RAGE-binding protein EN-RAGE, uPA and IL18R1." (PMID 41510260, 2025). "The combination of both TMAO and CFT073 had significant additive effects on the release of IL-18R1 and synergistic effects on the release of IL-6, IL-24, IL-33, LIF, TGF-α, and LAP TGF-β1 compared to CFT073 infection alone." (PMID 37111409, 2023). "Upregulation of ICOS, CXCR3, CXCR6, IL-18R1, and Chil3 in the brains of T. gondii-infected SCID mice that received a transfer of CD8+ immune T cells at 6 weeks after infection." (PMID 32291349, 2020). "Interestingly, 100% of IL-1R1- or IL-18R1-deficient mice survived infection by rMA15 (data not shown) indicating that the genetic absence of either receptor did not recapitulate the lethal phenotype observed following infection of MyD88−/− mice." (PMID 19079579, 2008).
infection (continued). "With IFNγ blockade, genes in cluster 2, including IL18R1, IDO1, CXCL11, CD274 (PD-L1), and PTPN2, were similarly expressed at day 3 post-infection but were more highly expressed at day 7 compared to controls and had increased expression over the day 3 timepoint." (PMID 38950078, 2024). "At this time point of infection, around 50% of CD44hiCD4+ T cells express the master gene of Th1 cells, T-bet, and the majority of T-bet+CD44hiCD4+ T cells expresses IL-18R1 but not IL-1R1." (PMID 28895840, 2017). "Although we have not studied the memory response in the infection model here, we also found a significant lower percentage of cells expressing high levels of the CD44 activation/memory marker among CD4+ T cells lacking IL-1R expression, as well as among Myd88−/− and Il18r1−/−CD4+ T cells." (PMID 28895840, 2017).
tumor (36 papers, 2016 to 2026). "We sorted tumor CD44hiCD103−CXCR6+PD-1+ TEff/EM cells and CD103−IL7R+IL18R1+ TEff/EM cells, as well as tumor and distant TRMs (CD103+CD69+) for repertoire analysis and clonotype lineage tracing." (PMID 33979626, 2021). "This was further corroborated by the robust anti-tumor response of CTXpre/CD4post-experienced Il18r1 KO mice, in which the highly functional IL-18Rαhi subset is only present in ex-T, but not in en-T cells." (PMID 34493727, 2021). "NOTCH2NL, MYBL2, and UBE2T were reported to be involved in tumorigenesis, while CXCR4 and IL18R1 were associated with immune response and pathway activation, indicating SRSF1 may take part in MM progression via tumor-related pathways." (PMID 37206090, 2023). "Moreover, IL18R1 deletion could enhance tumor growth and burden, and it increased the tumor burden in the carcinogen-induced liver cancer model." (PMID 36544782, 2022). "IL18R1 and TRIM antibodies were positive in all tumour samples, although some variability was observed in number and staining intensity of positive cells." (PMID 35201443, 2021). "Moreover, mature FOXP3+ Tregs in the tumor express CXCR6, IL21R, IL1R1, IL18R1, and, to a lesser extent, CCR8." (PMID 40164596, 2025). "However, RNA-seq analysis of tumor tissue from dogs before and following treatment indicated significant upregulation of KLRA1, KLRB1, NCR3 IL18R1, and TNFα at selected timepoints." (PMID 38379924, 2024). "The use of Il18r1 KO mice or anti-IL-18 treatment did not result in significant differences in tumor growth rate and survival among CTXpre-experienced groups (WT-CTXpre, WT-CTXpre + αIL-18, Il18r1 KO-CTXpre), which had low proportion of IL-18Rαhi T cells." (PMID 34493727, 2021). "In addition, we found that both CXCR6−IL7R+IL18R1+ and CXCR6+PD-1+ subsets shared TCR clonotypes with tumor TRMs." (PMID 33979626, 2021). "In addition, depletion of IL18R1, an IL18 receptor, has been shown to enhance tumor growth due to inhibitory recruitment of tumor-infiltrating lymphocytes." (PMID 29215599, 2017). "In addition, IL18R1 overexpression significantly inhibited the SK-MES-1 cell invasion and migration by scratch and Transwell assays, suggesting that IL18R1 acts as a tumor suppressor in LUSC progression." (PMID 36544782, 2022). "Furthermore, knocking down of IL18R1 in HOS and SJSA-1 cells showed similar effects with IL-18BP treatment on suppressing CD47 expression, enhancing macrophage infiltration and activation and inhibiting tumor growth." (PMID 36274066, 2022). "To validate this tumor-retention mechanism, we sorted CXCR6+PD-1+ and IL7R+IL18R1+ precursor populations from the tumors of CD45.1+ congenically marked BALB/c mice and intratumorally transferred equal numbers into a 4T1 tumor growing in the mammary tissue of Rag2KO BALB/c mice." (PMID 33979626, 2021).
cancer (17 papers, 2011 to 2026). A tumor composed of atypical neoplastic, often pleomorphic cells that invade other tissues. "Among the 32 LUSC tissue samples, five (15.625%) cancer tissue samples showed a significant increase in the IL18R1 expression levels." (PMID 36544782, 2022). "Conversely, the different cell lines showed variable expression of LTB and IL18R1, as already reported in different epithelial and carcinoma cells." (PMID 35201443, 2021). "Out of these SNPs, several occur in genes associated with behavior (Scn10A), metabolism (Ppgca1b), cancer (Brca2), and immune response (Map3k1, OAS2, IL18R1)." (PMID 21668978, 2011). "Overexpression of IL18R1 might influence the PD-1/PD-L1 inhibitory pathways, potentially leading to immune evasion by cancer cells." (PMID 40484866, 2025). "Therefore, we aimed to investigate the functions of IL18R1 in LUSC progression and the association between the immune microenvironment and IL18R1 expression to identify patients with cancer who would benefit from the prognosis." (PMID 36544782, 2022). "IL18R1 overexpression inhibits the growth and migration of cancer cells in LUSC." (PMID 36544782, 2022). "Between GM-CSF and IL18R1, we explored GM-CSF as a potential target, as it is a secretory cytokine in nature with the capacity to transform adjacent epithelial cells in a paracrine manner and whose role is well established in progression of a few cancer types." (PMID 34774800, 2022). "Notably, the treatments altered the gene expression of several tumorigenic and immunologic mediators, including MSXI, ZRSR2, GALNTL6, IL24, and IL18R1, which may impact cancer cell behavior." (PMID 42158898, 2026). "Two individual genes of module 6 were associated with treatment response, with IL18R1 being associated with good treatment response and IL1RAP being associated with poor response, in agreement with previous biological understanding of the IL18 and IL1 axes in cancer therapy." (PMID 38480759, 2024). "In contrast, the biomarkers uPA, IL-18R1, EN-RAGE, CASP-8, MCP-2, TNFβ, CD5 and CXCL10, whose functions are related to cancer or inflammatory processes, had their expression inhibited." (PMID 39247198, 2024). "Between CSF-2 and IL18R1, we chose to study CSF-2 as a potential target of PELP1 because of its proven role in cancer progression and as a secretory paracrine mediator." (PMID 34774800, 2022). "Many of these genes function in inflammation (CXCR3, EOMES, IL18R1, GZMM, IL2rb), metastases (CXCR3, BUB1), poor outcome cancers (EOMES, BUB1), or stem cells (EOMES, BUB1)." (PMID 22053823, 2011).
metabolic disease (4 papers, 2017 to 2025). A congenital disorder (due to inherited enzyme abnormality) or acquired (due to failure of a metabolically important organ) disorder resulting from an abnormal metabolic process. "GM dysbiosis and inflammation also induce epigenetic alterations in cytokine genes, such as IL-1β, IL-6, TNF-α, NF-kB, BTLA, IL-18R1, TGF-β, P13k/Akt1, Ctnnb1, and Hsp90aa1, as well as DNMTs, HDACs, and DAT1 associated with the development and progression of metabolic disorders and/or NPDs." (PMID 41228440, 2025).
head and neck tumors (1 paper, 2024). "In this study, it was found that IL-1α, IL-1β, IL1R1, IL1RL1, IL1F10, IL33, CASP1, and AIM2 were highly expressed in head and neck tumors, while IL1RN, IL1RAPL1, IL1RAPL2, IL18BP, IL18R1, and IL18RAP were low in expressed, which is consistent with previous literature." (PMID 39461030, 2024).
inflammation (1 paper, 2019). Aberrant reaction of the microcirculation characterized by movement of fluid and leukocytes from the blood into extravascular tissues. "Intriguingly, we observed that 32 targeted mRNAs were enriched in immune related functions and several mRNAs (e.g., Ccl1 and Il18r1) were related to liver inflammation and fibrosis." (PMID 31269941, 2019).
IL18R1 also shares sentences with these, for which no sentence is quoted: bacterial infection (7 papers); influenza (6); Insulin resistance (6); lung fibrosis (6); rheumatoid arthritis (5); Arthritis (4); acute kidney injury (3); allergic disease (3); eosinophilia (3); Hypertension (3); lupus (3); nephritis (3); periodontitis (3); allergic asthma (2); allergic rhinitis (2); cervical cancer (2); co-infection (2); dyslipidemia (2); experimental autoimmune encephalomyelitis (2); insulin dependent diabetes mellitus (2); neuropathies (2); primary Sjögren’s syndrome (2); respiratory disease (2); schizophrenia (2); small cell lung carcinoma (2); steatosis (2); type 2 diabetes (2); adenomyosis (1); adult-onset Still disease (1); Allergy (1).
A further 77 diseases each share a sentence with IL18R1 in 1 paper.